LCA5 (lebercilin LCA5)
Description:
Involved in intraflagellar protein (IFT) transport in photoreceptor cilia. Plays a role in the ciliary transport of photoreceptors outer segment proteins.
Synonyms: C6orf152
Tractability: No criterion of Open Targets' tractability assessment is met for any kind of drug.
Gene: Protein-coding gene on chromosome 6 (79,484,991 to 79,545,138, reverse strand). Ensembl gene ENSG00000135338.
Subcellular location: Cytoplasm, cytoskeleton; Cytoplasm, cytoskeleton, cilium axoneme; Cytoplasm, cytoskeleton, cilium basal body; Cytoplasm, cytoskeleton, microtubule organizing center, centrosome; Cell projection, cilium
Subcellular location (Human Protein Atlas): Centriolar satellite; Primary cilium tip; Cytosol; Golgi apparatus
Gene Ontology:
Molecular function: protein binding; protein-containing complex binding
Biological process: intraciliary transport; photoreceptor cell maintenance
Cellular component: ciliary tip; cilium; photoreceptor connecting cilium; axoneme; ciliary basal body; centrosome; cytoskeleton
Genetic constraint (gnomAD): Loss-of-function variants: 31 observed, 47.36 expected, observed/expected ratio (o/e) 0.65, 90% interval 0.49 to 0.88. The upper end of that interval is the gene's LOEUF score, 0.88, which puts it in group 3 of 6, group 1 being the genes least tolerant of losing a copy. Missense variants: 761 observed, 792.23 expected, observed/expected ratio (o/e) 0.96, 90% interval 0.9 to 1.02. Synonymous variants: 289 observed, 285.81 expected, observed/expected ratio (o/e) 1.01, 90% interval 0.92 to 1.12.
Gene-disease validity (ClinGen):
ClinGen rates the evidence that LCA5 causes each of these diseases.
LCA5-related retinopathy (autosomal recessive): Definitive. A retinopathy caused by biallelic variants in the LCA5 gene.
Homologues: Orthologues: chimpanzee LCA5 (99% identical), macaque LCA5 (95% identical), dog LCA5 (84% identical), rabbit LCA5 (81% identical), pig LCA5 (81% identical), guinea pig LCA5 (73% identical), mouse Lca5 (69% identical), rat Lca5 (69% identical), tropical clawed frog lca5 (37% identical), zebrafish lca5 (32% identical), Drosophila melanogaster CG6652 (15% identical). Paralogues in human: LCA5L (24% identical).
Diseases named in the same sentence as LCA5 in open-access papers:
LCA5 is named in the same sentence as 21 diseases in open-access papers, as found by Europe PMC text mining. Sharing a sentence is not in itself a finding about the gene and the disease. The quoted sentences say what the papers report.
Leber congenital amaurosis (15 papers, 2008 to 2025). Leber congenital amaurosis (LCA) is a retinal dystrophy defined by blindness and responses to electrophysiological stimulation (Ganzfeld electroretinogram (ERG)) below threshold, associated with severe visual impairment within the first year of life. "The LCA5 gene is associated with Leber congenital amaurosis (LCA), a hereditary retinal disease that severely affects vision." (PMID 40091069, 2025). "Bialleleic pathogenic variants in LCA5 cause one of the most severe forms of Leber congenital amaurosis, an early-onset retinal disease that results in severe visual impairment." (PMID 39934925, 2025). "Leber congenital amaurosis associated with pathogenic variants in LCA5 is a rare retinal dystrophy that causes photoreceptor dysfunction within the first months of life, but currently there are no available treatments." (PMID 39934925, 2025). "The fact that the CC is mostly preserved from microtubule collapse in Ccp1−/− and Ccp5−/− mice is highly similar to what we previously observed for the deficiency of the bulge protein Lebercilin (LCA5), causing Leber Congenital Amaurosis in human." (PMID 39528655, 2024). "Mutations in the lebercilin-encoding gene LCA5 cause one of the most severe forms of Leber congenital amaurosis, an early-onset retinal disease that results in severe visual impairment." (PMID 37305852, 2023). "Afanasyeva and colleagues used CRISPR-Cas9 gene editing to correct a mutation in LCA5 in patient-derived iPSCs, generating a cellular model for studying Leber congenital amaurosis." (PMID 37305852, 2023). "Mutations in the LCA5 gene disrupt its cognate ciliary protein lebercilin, causing Leber congenital amaurosis (LCA), one of the most severe forms of inherited blindness." (PMID 37071472, 2023). "Homozygous mutations of LCA5 gene are associated with Leber congenital amaurosis, which is prominently an autosomal recessive heterogeneous disorder." (PMID 35713440, 2022). "Mutations in the Leber congenital amaurosis 5 (LCA5) gene (MIM 611408) are reported to cause one to two percent of patients with Leber congenital amaurosis (LCA)." (PMID 27067258, 2016). "This strategy has been performed in BBS consanguineous families to detect new genes, such as BBS9, BBS11, and BBS12; in other retinal pathologies, such as Leber congenital amaurosis, this strategy allowed the identification of novel mutations in the LCA5 gene." (PMID 20142850, 2010). "One of the most severe forms of LCA is linked to a protein lebercilin, encoded by the gene Leber Congenital Amaurosis 5 Protein (LCA5) that is localized within the CC of photoreceptor cells." (PMID 37305852, 2023). "LCA5 and RDH12 are associated with Leber congenital amaurosis (LCA), and MC is one of the phenotypes for LCA5-LCA and RDH12-LCA." (PMID 36429029, 2022). "The list included genes associated with different forms of Leber congenital amaurosis, involved in disruptions in phototransduction (AIPL1), retinoid cycle (RDH12, RPE65), and transport across the photoreceptor connecting cilium (LCA5), as well as genes evidently interacting with AIPL1 (NUB1, AHR)." (PMID 38203368, 2023). "Mutations in these ciliary genes are implicated in photoreceptor degeneration related ciliopathies, such as RPGRIP1 in cone dystrophy (CD)/cone-rod dystrophy (CRD), LCA5 and CEP290 in Leber congenital amaurosis (LCA), Fam161A and OFD1 in RP." (PMID 27196396, 2016).
ciliopathy (5 papers, 2008 to 2022). A genetic disorder of the cellular cilia or the cilia anchoring structures, the basal bodies, or of ciliary function. "In this work, we characterized the interaction of LC8 with the centrosomal protein lebercilin (LCA5), which is associated with a specific form of ciliopathy." (PMID 36114230, 2022). "LCA5 is known to be a ciliopathy, a disease resulting from a defect in formation or function of cilia." (PMID 18334959, 2008). "This is surprising as other ciliopathies affect the kidney and other organs, and the LCA5 gene is known to be expressed in nasopharynx, trachea, and lungs and was originally identified in the proteome of bronchial epithelium ciliary axonemes." (PMID 18334959, 2008). "NINL has been previously shown to bind several other ciliopathy proteins present at the base of cilia, specifically LCA5 and USH2A, suggesting that it may play a more pivotal role in vesicular trafficking in photoreceptors than CC2D2A." (PMID 26485645, 2015). "Furthermore, the signature included genes whose mutations are known to cause ciliopathies with dysfunctions of primary cilia (e.g. ARL6, LCA5, TMEM67)." (PMID 22558177, 2012).
retinal degeneration (5 papers, 2009 to 2022). Degeneration of the retina. "In summary, we describe a Pakistani family with Leber congenital amaurosis linked to the LCA5 locus, and the identification of a novel frameshift mutation confirms LCA5 as contributor to congenital retinal degeneration." (PMID 21850168, 2011). "This highly conserved domain is predicted to bind to microtubules as well as proteins linked to retinal degeneration and ciliary trafficking, such as CEP290, OFD1, and LCA5." (PMID 36233334, 2022). "We identified a total of nine causal mutations, including six novel variants in RPE65, LCA5, USH2A, CNGB1, FAM161A, CERKL and GUCY2D as the underlying cause of inherited retinal degenerations in 13 of 26 pedigrees." (PMID 26352687, 2015). "Consistent with the phenotype observed in the cohort of patients analyzed in this study, the RPE65, LCA5, USH2A, CNGB1, FAM161A, CERKL and GUCY2D genes consisting mutations in 13 of the 26 pedigrees have been implicated in causing recessive non-syndromic retinal degeneration." (PMID 26352687, 2015). "There is consensus that LCA5 mutations lead to an early and severe visual disturbance with nystagmus, abnormal visual acuity, nondetectable electroretinograms, and fundus features of retinal degeneration." (PMID 19503738, 2009).
retinal ciliopathies (4 papers, 2015 to 2025). "In summary, iPSC-derived retinal organoids are a powerful model for investigating the molecular and cellular changes associated with loss of LCA5 function and highlight the therapeutic potential of small molecules to treat retinal ciliopathies." (PMID 39934925, 2025). "Moreover, a retinal ciliopathy protein Lebercilin (LCA5) associates with the IFT machinery to modulate photoreceptor opsin trafficking." (PMID 26501325, 2015). "There are now several more genes being targeted for gene therapy in retinal ciliopathies including CEP290 (mutations in which cause LCA10); and LCA5." (PMID 30915099, 2019).
retinal disease (4 papers, 2023 to 2025). "Here, we report on the generation of a patient-specific cellular model to study LCA5-associated retinal disease." (PMID 37305852, 2023). "Given the retina-specific phenotype observed with mutations of LCA5, unraveling the function of the bulge protein lebercilin could bring insights into the role of the bulge region in context of specific forms of inherited retinal diseases (IRDs)." (PMID 37071472, 2023).
cone dystrophy (3 papers, 2016 to 2017). An inherited ocular disorder characterized by the loss of cone cells, the photoreceptors responsible for both central and color vision. "Herein, according to a comprehensive genetic screening approach, we describe two novel LCA5 mutations in a previously unreported correlation with cone dystrophy (CD) in two affected siblings from a Chinese family with autosomal recessive inheritance pattern." (PMID 27067258, 2016).
cone-rod dystrophy (2 papers, 2016 to 2024). Inherited retinal dystrophies that belong to the group of pigmentary retinopathies. "The other IRD group included Stargardt's disease carrying ABCA4 variants, as well as individuals with Cone-Rod Dystrophy (CORD) or RP presenting with various genetic variants such as RDH12, RPGR, LCA5,CEP290, RP2, USH2A, and EYS." (PMID 38466290, 2024).
retinal dystrophies (2 papers, 2016 to 2025). "LCA5 mutations have been reported to cause several forms of inherited retinal dystrophies, but have never been found correlated with CD." (PMID 27067258, 2016).
acute coronary syndrome (1 paper, 2021). Signs and symptoms related to acute ischemia of the myocardium secondary to coronary artery disease. "Variants in LCA5 gene were shown to modify glucose response in a clinical trial of insulin and potassium (GIK) infusion in acute coronary syndromes." (PMID 33472578, 2021).
cataract (1 paper, 2011). Partial or complete opacity of the crystalline lens of one or both eyes that decreases visual acuity and eventually results in blindness. "In a recent study on 14 LCA families (3 families linked to LCA5) from Northern Pakistan, the prevalence of cataracts in LCA5 was estimated to be 8%." (PMID 21850168, 2011). "Our study suggests that cataracts may also be an early feature in LCA5-linked LCA." (PMID 21850168, 2011). "In that study, cataracts represent a late-onset feature of LCA5 and did not manifest before the second decade of life." (PMID 21850168, 2011).
choroideremia (1 paper, 2024). Choroideremia (CHM) is an X-linked chorioretinal dystrophy characterized by progressive degeneration of the choroid, retinal pigment epithelium (RPE) and retina. "Treatment of LCA5 gene-dependent LCA (type 5) is similarly advanced, while a so-called “molecular photoswitch”, conferring light-sensing capabilities to special types of retinal neuron cells, could potentially become a new treatment in RP and choroideremia." (PMID 39202371, 2024).
congenital blindness (1 paper, 2025). "One of the key connecting cilia proteins is lebercilin, encoded by the gene LCA5, whose function is disrupted in a condition causing congenital blindness (Leber congenital amaurosis type 5, LCA5)." (PMID 41164956, 2025).
Developmental cataract (1 paper, 2011). A cataract that occurs congenitally as the result of a developmental defect, in contrast to the majority of cataracts that occur in adulthood as the result of degenerative changes of the lens. "Developmental cataracts were present in two of the four patients, raising the possibility that LCA5 mutations may predispose to this additional ocular pathology." (PMID 21850168, 2011).
myopia (1 paper, 2025). "Subsequently, RIMS2 [odds ratio (OR) = 0.01, P = 0.0097] and LCA5 (OR = 9.27, P = 0.0089) were found to harbor an excess number of nonsynonymous variants in patients with slow progression of high myopia." (PMID 40091069, 2025).
retinopathy (4 papers, 2016 to 2025). "Genome-editing approaches using CRISPR/Cas9 have rescued the disease phenotype in iPSCs from patients with RP, XLRS, LCA4, LCA5, enhanced S-cone syndrome, or nonsyndromic retinopathy harboring CLN3 mutations, by revealing differentiation into ROs." (PMID 39422807, 2025). "Our study extends the phenotypic and genotypic spectrums for LCA5-associated retinopathies and better illustrates its genotype-phenotype correlations, which would help with better genetic diagnosis, prognosis, and personalized treatment for CD patients." (PMID 27067258, 2016). "In summary, we have identified novel LCA5 mutations in the etiology of CD, which extends the phenotypic and genotypic spectrums for LCA5-associated retinopathies." (PMID 27067258, 2016). "Therefore, this study provides evidence that small molecule treatments could be a potential therapeutic intervention for LCA5-associated retinopathy." (PMID 39934925, 2025). "LCA5 mutations have not been reported in causing other forms of retinopathies, especially cone dominant dystrophies." (PMID 27067258, 2016).
respiratory disease (1 paper, 2008). "The cause of death in this child may therefore imply that LCA5 mutations can in fact cause a wider spectrum of phenotypes including respiratory disease." (PMID 18334959, 2008).
LCA5 also shares sentences with these, for which no sentence is quoted: Blindness (1 paper); inherited diseases (1); keratoconus (1); Stargardt disease (1); Usher syndrome (1).